PDPN (podoplanin)
Diseases named in the same sentence as PDPN in open-access papers (continued):
Sharing a sentence is not in itself a finding about the gene and the disease.
cancer (continued). "PDPN is a specific lymphatic endothelium marker, which is frequently expressed in some types of malignant tumors, including brain tumors, squamous cell carcinoma, and malignant mesothelioma, and can be used as a diagnostic marker in cancer." (PMID 38167452, 2024). "Thus, the inhibitor targeting these factors showed a promising effect on reversing podoplanin-positive cancer-associated fibroblasts-induced suppression of NK cells mediated ADCC." (PMID 39482550, 2024). "PDPN may therefore represent an attractive putative target for therapies that aim to simultaneously reduce cancer progression and associated VTE." (PMID 40741180, 2024). "The expression of PDPN has been linked to poor prognosis in cancer, and is hypothesised to play roles in invasion, epithelial to mesenchymal transition (EMT) and metastasis." (PMID 38582812, 2024). "Furthermore, the involvement of CLEC-2 in the hematogenous metastasis of PDPN-producing cancer cells and cancer-associated thrombosis has been demonstrated in a murine model of experimental carcinogenesis." (PMID 37569299, 2023). "In addition, PDPN+ CAFs induce primary resistance to EGFR tyrosine kinase inhibitor (EGFR-TKI) in LUAC with EGFR mutation by activating the MAPK signaling pathway in cancer cells." (PMID 37143134, 2023). "PDPN is also utilized as a biomarker for CAFs, and its overexpression in CAFs, epithelial tumor cells, and inflammatory macrophages is associated with worse outcomes in many cancers." (PMID 37809094, 2023). "Moreover, high PDPN expression was reported to be associated with shortened survival of different cancer patients, Despite that PDPN can be induced upon TGFβ stimulation, the detailed crosstalk between TGFβ and PDPN has not been extensively elucidated." (PMID 37898647, 2023). "Through the C‐type lectin receptor‐2, malignant endothelial cells express a protein, known as Podoplanin, that activates platelets and accelerate thrombosis although the role of Podoplanin in cancer‐associated thrombosis was only described in intracranial malignancies." (PMID 36314077, 2023). "Consistently, a positive association between PDPN‐positive CAFs and lymphocyte infiltration was reported in other cancer types, suggesting that PDPN expression in CAFs may be an indicator of immunogenic tumors." (PMID 36102377, 2022). "A growing number of pre-clinical investigations have been reported because PDPN could be a useful diagnostic marker and an attractive molecular target for cancer therapy." (PMID 35159384, 2022). "Podoplanin (Pdpn) is a mucin-type transmembrane protein that has been implicated in multiple physiological settings including lymphangiogenesis, platelet aggregation, and cancer metastasis." (PMID 34707599, 2021). "Increased expression of PDPN in cancer cells is associated with a high risk of thrombosis." (PMID 34322381, 2021). "PDPN acts as a molecular marker specific for lymphatic vessels and, because there is a correlation shown to exist between the formation of lymphatic vessels and poor cancer prognosis, it is also frequently used as a diagnostic marker for cancer." (PMID 32858947, 2020). "The identification of the cancer-associated phenotype was corroborated via podoplanin staining." (PMID 32384738, 2020). "In addition to the protective roles described, podoplanin is commonly upregulated in pathogenic tissues [e.g. rheumatoid joint, various cancers] where it is believed to play a role in pathology." (PMID 30745334, 2019). "However, the overexpression of podoplanin and its potential role in cancer-associated thrombosis has also been shown in other kinds of tumors, such as lung or breast." (PMID 31212608, 2019). "Also in different types of cancers, for instance in squamous cell carcinoma, lung and skin cancer, mesotheliomas, and cancer-associated fibroblasts, an upregulated expression of podoplanin was detected." (PMID 30305116, 2018).
cancer (continued). "Previous studies indicated that PDPN may also be expressed by cancer-associated fibroblasts or macrophages." (PMID 30592710, 2018). "Due to its elevated expression and requirement for CSC induction and tumorigenesis, we suggest that podoplanin may be used as a predictive biomarker for cancer risk assessment and for safer by design screening of CNTs and related nanomaterials." (PMID 27996035, 2016). "A proportion of podoplanin-positive cancer cells also expressed vimentin, suggesting that podoplanin may result in vimentin-associated EMT." (PMID 26095281, 2015). "Moreover, we report that human OSCC cells formed tumors that expressed PDPN in mice, and induced PDPN expression in infiltrating host murine cancer associated fibroblasts." (PMID 25826087, 2015). "Moreover, deregulated expression and/or activation of MMPs, podoplanin, p21Rac1, and/or vimentin are often associated with poor prognosis in many cancers." (PMID 24598827, 2014). "Given that podoplanin expression is often associated with cancer cell motility, migration and invasion, a recent report demonstrated that PKA phosphorylation of serines in the intracellular tail of podoplanin infact interfered with the ability of podoplanin to regulate cell motility and migration." (PMID 24598827, 2014). "Interestingly, PDPN is also upregulated by cancer-associated fibroblasts (CAFs) in the stroma surrounding various tumors, including adenocarcinomas and colorectal cancers." (PMID 22988448, 2012). "Therefore, CLEC-2-podoplanin interactions can stimulate cancer-associated thrombosis." (PMID 37693009, 2023). "Thus, it remains unclear whether ROCK acts to positively or negatively regulate podoplanin-mediated migration in cancer-associated MSCs." (PMID 30745334, 2019). "In addition, podoplanin is also expressed by cancer associated fibroblasts (CAFs)." (PMID 31508790, 2019). "Premalignant lesions with podoplanin expression beyond the basal cell layer may represent truly early neoplastic lesions, enriched in TICs and with a higher risk of progression to invasive cancer." (PMID 20196862, 2010). "Knockdown of PDPN in cancer cells also resulted in reduced cell proliferation, migration, and invasion, suggesting the intricate roles of PDPN in cancer development." (PMID 39780187, 2025). "Previous studies have demonstrated that the binding of PDPN to its ligand CLEC-2 can contribute to cancer tumorigenesis, yet the function of the PDPN/CLEC-2 axis in CRC is unclear." (PMID 40693815, 2025). "Periostin (POSTN) and podoplanin (PDPN) are both proteins playing an important role in humans in the diagnosis and study of many malignant tumours." (PMID 41361308, 2025). "Blocking the binding of CLEC-2 to podoplanin can inhibit the growth of podoplanin-expressing cancer cells in vivo." (PMID 39852571, 2025). "Recently, clinical evidence has suggested that PDPN plays an important role during epithelial-to-mesenchymal transition (EMT) in a wide range of cancers." (PMID 40554484, 2025). "A single-cell transcriptomics analysis (TISCH2 database) revealed that TNFRSF12A is highly expressed in cancer-associated fibroblasts (CAFs) and positively correlated with CAF markers (FAP: ρ = 0.304; PDPN: ρ = 0.364)." (PMID 41300305, 2025). "Podoplanin proteins, released by cancer cells into the bloodstream, exert influence thrombosis at remote sites." (PMID 39759851, 2025). "This proposed mechanistic role is supported by consistent associations between PDPN and multiple immune checkpoint markers across independent transcriptomic datasets, including the TISIDB and TCGA pan-cancer cohorts." (PMID 41573582, 2025). "RT-qPCR and western blot analysis of PDPN gene and protein expression in matched primary carcinoma and NDT, confirmed the proteomic data." (PMID 40842027, 2025). "The immunohistochemical analysis revealed a strong and significant increase in stromal PDPN in the primary carcinoma compared to the normal tissue." (PMID 40842027, 2025).
cancer (continued). "This study revealed that the high expression of PDPN in CAFs was associated with histological grade and HER-2 status, indicating that PDPN has clear potential as a cancer biomarker and therapeutic target." (PMID 38410801, 2024). "The basement membrane containing type-IV collagen is well preserved in the superficial portion of CRC; however, it diminishes as the cancer invades deeper into the mucosa, mirroring the pattern of pericryptal/periglandular PDPN expression." (PMID 39451200, 2024). "The main feature of PDPN is to help cancer progression by blocking the death of tumoral cells and by sustaining cellular migration." (PMID 39057054, 2024). "The study also showed that syk tyrosine kinase is phosphorylated when platelets interact with PDPN-high cancer cells in vitro." (PMID 40741180, 2024). "In GBM, PDPN is connected to alterations in the genetic and epigenetic characteristics of cancer cells, and the specific factors responsible for these alterations are not well understood." (PMID 39682237, 2024). "Overexpression of the transcription factors Specificity protein 1 (Sp1) and Specificity protein 3 (Sp3) independently increases PDPN transcription in certain cancer cell lines." (PMID 39682237, 2024). "Those cancers with high expression of PDPN, MMP2 and THY1 were enriched for immune-mediated pathways, such as inflammatory response, IFN response, and IL6-JAK-STAT signaling." (PMID 39335130, 2024). "Almost 90 % of these cancer cells expressed TF and/or PDPN, along with necrosis, platelet aggregation, and fibrin formation." (PMID 40741180, 2024). "The expression of TF and PDPN in non-cancer cells and CD163-positive monocytes/macrophages was predominantly in the organizing thrombus area." (PMID 40741180, 2024). "We evaluated the presence of cancer-associated fibroblasts (CAFs) and subtypes associated with PDAC using subsets defined by podoplanin, aSMA and platelet-derived growth factor receptor (PDGFR), and found no significant changes in DRP-104-treated tumors." (PMID 37814010, 2024). "Cancer growth and metastases are prevented when mice are treated with the chimeric anti-PDPN antibodies ChMS-1 and hP2-0." (PMID 39451677, 2024). "Because PDPN also plays an essential role in normal cells such as kidney podocytes, cancer specificity is required to reduce adverse effects on normal cells." (PMID 39594582, 2024). "This study represented the first report to define a functional PDPN aptamer with the potential to interfere with platelet–cancer cell interactions mediated by the binding of PDPN to the platelet CLCE-2." (PMID 39451677, 2024). "Increased abundance of PDPN in CAFs is correlated with poor clinical outcomes in pancreatic, breast, and lung cancer patients." (PMID 39594582, 2024). "Cancers that have PDPN expression tend to be more deadly, as they have an increased capacity to generate stem cells, invade the surrounding tissues, and transition from epithelial to mesenchymal cells." (PMID 39682237, 2024). "The authors went on to show that PDPN-high cancer cells induced PF4 secretion in platelet-rich plasma, which was inhibited by SZ168, and that platelet-specific P-selectin expression was inhibited by SZ168." (PMID 40741180, 2024). "The potency of cancer metastasis and the embolization of cancer cells in the microvasculature of a lung are highly related to PDPN-induced platelet aggregation." (PMID 39451677, 2024). "As a biomarker of cancers, PDPN is correlated with more aggressive behavior, tumoral thickness, and invasiveness." (PMID 39057054, 2024). "PDPN-induced platelet aggregation is also involved in separation of the lymphatic and blood vasculatures during growth and development and in cancer metastasis." (PMID 40741180, 2024). "Interference of PDPN/CLEC-2 interactions by the small molecule inhibitors 2CP and cobalt–hematoporphyrin suppresses platelet activation and cancer-associated thrombosis." (PMID 39451677, 2024).
cancer (continued). "We further screened the reactivity to PDPN-positive cancer cell lines (PC-10 and LN319) and embryonic kidney 293FT cells using flow cytometry." (PMID 39594582, 2024). "In surgically resected human SCLC specimens, the frequency of geminin‐positive cancer cells was higher in the cases with PDPN‐positive CAF than in those with PDPN‐negative CAF." (PMID 39487962, 2024). "The system effectively screened out small-molecule inhibitors for cancer and thrombosis treatment by inhibiting the PDPN–CLEC-2 interaction." (PMID 38504248, 2024). "The expression of PDPN is upregulated in epithelial and mesenchymal cells during inflammation and cancer." (PMID 40741180, 2024). "We have developed CasMabs against HER2 (H2Mab-250), podocalyxin (PcMab-6), and podoplanin (LpMab-2 and LpMab-23) by evaluating the reactivity against cancer and normal cells in flow cytometry and immunohistochemistry." (PMID 39125956, 2024). "The platelet C-type lectin-like receptor 2 (CLEC-2) can bind podoplanin (PDPN) on a cancer cell surface to facilitate TCIPA." (PMID 39451677, 2024). "PDPN-positive CAFs generate tracks through Rho-ROCK pathway to assist with cancer cell invasion in the extracellular matrix." (PMID 36937386, 2023). "PDPN is a glycoprotein overexpressed in various cancers and a growing body of evidence indicates its relevant function in several fibrotic and inflammatory pathologies." (PMID 37298679, 2023). "PDPN-expressing cancers show aggressive phenotypes, including increased stemness, invasiveness, and epithelial-to-mesenchymal transition, which lead to malignant progression." (PMID 37894446, 2023). "We previously established cancer-specific mAbs (CasMabs) against podoplanin and podocalyxin, which are expressed in many cancers including OSCC." (PMID 36975491, 2023). "CLEC-2 and its endogenous ligand podoplanin (PDPN) promote hematogenous cancer metastasis and cancer-associated thrombosis." (PMID 37762054, 2023). "Podoplanin induces platelet activation by binding to CLEC-2, thereby facilitating cancer metastasis and cancer-associated thrombosis." (PMID 37569299, 2023). "PDPN plays an important role in various physiological and pathological processes, such as inflammation, thrombus formation and cancer progression." (PMID 36829453, 2023). "In particular, the authors evaluated the MIB-1 of podoplanin (+) and podoplanin (−) CAFs cancer cells to assess their MIB-1 index." (PMID 38026900, 2023). "Studies have also reported the role of podoplanin-Clec-2 interactions in cancer metastasis and prognosis." (PMID 37386100, 2023). "Human podoplanin (PDPN) is a type 1 transmembrane sialomucin-like glycoprotein that is upregulated in several cancer types." (PMID 37993428, 2023). "Elevated PDPN staining in CAFs is correlated with poor prognosis in lung, breast, and pancreatic cancer patients." (PMID 37894446, 2023). "PDPN-positive cancer cell lines stimulate platelet activation, particularly platelet TGFβ-expression, which induces cancer cells to undergo EMT." (PMID 37298230, 2023). "We previously developed PDPN-targeting CasMabs and podocalyxin-targeting CasMabs, which recognize cancer-type aberrant glycosylation of the targets." (PMID 37489367, 2023). "Further, in the bloodstream, CLEC-2-podoplanin can promote cancer cell evasion of the immune surveillance." (PMID 37693009, 2023). "PDPN-positive CAFs exhibit poor clinical outcomes in cancers of the lung, breast, pancreas, and esophagus." (PMID 36937386, 2023). "The transmembrane protein podoplanin found on the surface of many cancer cell types can directly interact with platelet activation receptor CLEC-2." (PMID 37770941, 2023). "Cancer-associated fibroblast (CAF) sub-clusters showing high expression of IL6, CCL2, S100A4, PDPN, and FGF7 were identified in both primary and metastatic samples." (PMID 38328306, 2023).
cancer (continued). "We previously developed PDPN-targeting cancer-specific mAbs (CasMabs) and podocalyxin-targeting CasMabs, which are currently being applied to CAR-T therapy in mice models." (PMID 37185762, 2023). "We developed podocalyxin-targeting CasMabs and PDPN-targeting CasMabs, which react with the aberrantly glycosylated targets selectively expressed in cancer." (PMID 37504249, 2023). "A cancer-specific anti-PDPN mAb, LpMab-23 (mouse IgG1, kappa), was established in our previous study." (PMID 37894446, 2023). "A cancer-specific monoclonal antibody against human podoplanin has been demonstrated to be an effective treatment strategy particularly in podoplanin-expressing malignancies." (PMID 36793738, 2023). "In fact, useful some monoclonal antibodies, LpMab, has been reported to specifically recognize abnormally glycosylated podoplanin on cancer cells." (PMID 37386100, 2023). "An anti-podoplanin CasMab, LpMab-2 can recognize the cancer-type aberrant glycosylation of Thr55 and/or Ser56 with surrounding peptide, which is not expressed in normal cells." (PMID 36975491, 2023). "Subsequently, the E#4 was defined as lymphatic endothelial (LEC) cells by the marker genes (LEC) (e.g., PDPN and PROX1), and E#1 was defined as carcinoma‐associated fibroblasts derived endothelial cells (CAFsEc) (e.g., S100A4)." (PMID 37726969, 2023). "Researchers discovered that podoplanin was upregulated in the venous wall while trying to figure out the mechanism of cancer-mediated inflammation." (PMID 35082906, 2022). "To precisely target GBM cells, we previously created a cancer-specific monoclonal antibody (CasMab) for human PDPN." (PMID 35991754, 2022). "Second, the discovery and characterization of several biomarkers including VEGF-C, LYVE-1, Podoplanin and Prox-1 have opened new vistas in the understanding of the induction of lymphangiogenesis by cancer cells." (PMID 34767139, 2022). "High podoplanin expression has been observed at the invasive front of tumors of different cancer types, where individual invading amoeboid cells are also observed." (PMID 36278174, 2022). "Transfection studies with cultured normal and cancer cells in vitro support that podoplanin expression in human cancers promotes migration and invasion of cancer cells and metastasis to regional lymph nodes in vivo." (PMID 36247509, 2022). "This antibody's utility in podoplanin-expressing cancers has been demonstrated in previous literature." (PMID 36247509, 2022). "We previously established cancer-specific mAbs (CasMabs) targeting podoplanin and podocalyxin, which are expressed on many tumors." (PMID 35735360, 2022). "We constructed a novel CasMab-based CAR T cells that targets the cancer-specific PDPN in GBM cells in this study." (PMID 35991754, 2022). "In collagen invasion assay, podoplanin (PDPN)‐expressing CAFs invade the collagen matrix, and then cancer cells invade within the footpaths created by CAFs." (PMID 35603909, 2022). "A CasMab, Lp2 was purified from a human PDPN-transfected GBM cell line and recognizes cancer-type PDPN." (PMID 35991754, 2022). "As a cancer cell-targeting agent, panitumumab was used for mEERL-hEGFR tumors, and anti- PDPN mAb was used for MOC1 tumors." (PMID 36465486, 2022). "We investigated the potential relationship between cell membrane expression of PDPN and the putative cancer cell surface stem cell marker CD133." (PMID 36059614, 2022). "Recently reported, CD177 can regulate PDPN and thus affect the physiological changes of cancer-related fibroblasts, which seems to be a new therapeutic target." (PMID 36401283, 2022). "We previously established cancer−specific mAbs (CasMabs) targeting to PDPN and podocalyxin, which are expressed on many cancers, including ESCC." (PMID 35628345, 2022). "A novel monoclonal antibody (mAb) clone, LpMab-2 (Lp2), recognizes the aberrantly glycosylated cancer-type PDPN, which was extracted from a human PDPN-transduced GBM cell line." (PMID 35991754, 2022).